MIR1248 (microRNA 1248)
Synonyms: hsa-mir-1248; MIRN1248; mir-1248
Gene: MicroRNA gene on chromosome 3 (186,786,672 to 186,786,777, forward strand). Ensembl gene ENSG00000283958.
Gene Ontology:
Biological process: RNA processing
Cellular component: nucleolus
Homologues: Orthologues: chimpanzee ptr-mir-1248 (100% identical).